DIRAS3 (DIRAS family GTPase 3)
Synonyms: ARHI; NOEY2
Tractability: Small molecule: a structure with a bound ligand is known. Antibody: UniProt places it where antibodies can reach, with high confidence; its Gene Ontology location is reachable by antibodies, with medium confidence.
Gene: Protein-coding gene on chromosome 1 (68,045,886 to 68,051,717, reverse strand). Ensembl gene ENSG00000162595.
Subcellular location: Cell membrane
Subcellular location (Human Protein Atlas): Cytosol; Nuclear membrane
Gene Ontology:
Molecular function: protein binding; GTPase activity; GTP binding
Biological process: genomic imprinting; regulation of cyclin-dependent protein serine/threonine kinase activity; small GTPase-mediated signal transduction; signal transduction
Cellular component: plasma membrane; membrane
Genetic constraint (gnomAD): Loss-of-function variants: 0 observed, 0.47 expected, observed/expected ratio (o/e) 0, 90% interval 0 to 1.84. That is too few expected variants to judge how well the gene tolerates losing a copy. Missense variants: 248 observed, 316.37 expected, observed/expected ratio (o/e) 0.78, 90% interval 0.71 to 0.87. Synonymous variants: 133 observed, 140.16 expected, observed/expected ratio (o/e) 0.95, 90% interval 0.82 to 1.1.
Homologues: Orthologues: chimpanzee DIRAS3 (100% identical), macaque DIRAS3 (91% identical), pig DIRAS3 (63% identical). Paralogues in human: DIRAS2 (42% identical), DIRAS1 (40% identical), RAP1B (28% identical), RASD2 (28% identical), RRAS2 (28% identical), RAP1A (27% identical), RAP2A (26% identical), MRAS (26% identical), RAP2B (26% identical), GEM (25% identical), RALB (25% identical), RRAD (25% identical), and 23 more.
Diseases named in the same sentence as DIRAS3 in open-access papers:
DIRAS3 is named in the same sentence as 43 diseases in open-access papers, as found by Europe PMC text mining. Sharing a sentence is not in itself a finding about the gene and the disease. The quoted sentences say what the papers report.
ovarian carcinoma (42 papers, 2005 to 2025). A malignant neoplasm originating from the surface ovarian epithelium. "It was reported that in human patients with breast cancer and ovarian cancer, hypermethylation in both CpG islands, I and II, was associated with reduced expression of DIRAS3." (PMID 34063661, 2021). "Re-expression of DIRAS3 induces tumor dormancy in human ovarian cancer xenografts in immune deficient mice." (PMID 31052266, 2019). "We have identified an autophagy-inhibiting peptide based on the switch II region of DIRAS3 linked to Tat peptide that is taken up by ovarian cancer cells, binds Beclin1 and inhibits starvation-induced DIRAS3-mediated autophagy." (PMID 31003488, 2019). "ARH1 (Aplasia Ras Homolog member I; also known as DIRAS3), which encodes a ras-homolog 26 kDa GTPase, is a tumor suppressor gene imprinted down-regulated in ovarian cancers." (PMID 22974323, 2012). "Similar cytotoxic role of autophagy was also reported that enforced expression of an imprinted tumor suppressor gene GTP-binding RAS-like 3 (DIRAS3 or ARHI) in DIRAS3-deficient ovarian cancer cells may induce autophagy and tumor dormancy." (PMID 25402829, 2014). "FN was found to inhibit DIRAS3-induced autophagy and to partially rescue ovarian cancer cells from DIRAS3-induced cell death while reducing DIRAS3-induced inhibition of p-FAK and p-AKT." (PMID 40862729, 2025). "Elements of the extracellular membrane (ECM), such as FN, can rescue ovarian cancer cells from DIRAS3-induced autophagic death in vitro." (PMID 40862729, 2025). "Our previous studies have shown that re-expression of the tumor suppressor gene DIRAS3 inhibits growth of ovarian cancer cells, promotes autophagic cell death in vitro, and induces tumor dormancy in vivo." (PMID 40862729, 2025). "The re-expression of the tumor suppressor gene ARHI (DIRAS3), which is frequently downregulated in ovarian cancer, promotes autophagy by inhibiting the PI3K/AKT/mTOR pathway and upregulating ATG4." (PMID 41404065, 2025). "Inhibiting the FAK signaling pathway enhanced DIRAS3-induced autophagy, leading to ovarian cancer cell death, both in vitro and in vivo." (PMID 40862729, 2025). "Defactinib, a pharmacologic inhibitor of FAK, enhanced DIRAS3-induced autophagy in ovarian cancer cells cultured with fibronectin." (PMID 40862729, 2025). "Inhibiting FAK with defactinib in ovarian cancer cells enhanced DIRAS3-induced autophagy and cell death." (PMID 40862729, 2025). "Our findings suggest that ECM components in the tumor microenvironment like FN enhance the activities of β1 integrin, FAK, and AKT to inhibit DIRAS3-induced autophagic cell death, thereby promoting ovarian cancer cell survival." (PMID 40862729, 2025). "DIRAS3 re-expression in ovarian cancer cells suppresses proliferation, motility, and growth as xenografts." (PMID 40862729, 2025). "When DIRAS3 was re-expressed in human ovarian cancer xenografts, tumors remained dormant, but when levels of DIRAS3 were reduced, tumors grew rapidly." (PMID 40862729, 2025). "Persistent ovarian cancer cells from positive second look operations upregulate DIRAS3 and undergo autophagy." (PMID 40862729, 2025). "Studies demonstrate that in ovarian cancer microenvironments, DIRAS3-dependent autophagy sustains dormant cancer cell viability under nutrient deprivation, suggesting its involvement in therapy resistance through metabolic adaptation." (PMID 40649981, 2025). "Re-expression of DIRAS3 induced autophagic cell death in cultured ovarian cancer cells, consistent with autophagy tumor suppressor function." (PMID 40862729, 2025). "Autophagy was also measured by fluorescence microscopy, where LC3B staining detected an increase in LC3 puncta after DOX-induced DIRAS3 re-expression in SKOv3-DIRAS3 ovarian cancer cells." (PMID 40862729, 2025). "The downregulation of DIRAS3 is seen in cancers of the ovary, breast, lung, prostate, colon, brain, and thyroid." (PMID 40649981, 2025).
ovarian carcinoma (continued). "In ovarian cancer, elimination of autophagy mediated by DIRAS3 and ULK1 via the lncRNA RNF157-AS1 reduced the resistance of ovarian cancer cell resistance to DDP." (PMID 38933333, 2024). "D.B. Badgwell and colleagues reported that DIRAS3 suppresses the migration of ovarian cancer cells via the STAT3 and FAK/Rho signaling pathways." (PMID 36805591, 2023). "For example, the re-expression of the tumor suppressor Aplasia Ras homolog member 1 (ARHI; DIRAS3) in breast and ovarian cancer cells prevents apoptotic cell death and promotes dormancy by inducing autophagy and altering fundamental metabolic pathways." (PMID 35158815, 2022). "A frequently downregulated tumor suppressor gene in ovarian cancer, DIRAS3, has been illustrated to facilitate autophagy induced by amino acid deprivation in the presence or absence of serum." (PMID 35008317, 2021). "In the ovarian cancer dormancy model, induction of DIRAS3 resulted in a higher glycolytic rate and mitochondrial respiration rate was decreased." (PMID 33816262, 2021). "DIRAS3/ARHI usually has a lower expression level in ovarian cancer cells, but the re-expression of DIRAS3 induces autophagy and these cells keep dormant when they grow in a mouse model." (PMID 34829881, 2021). "In DIRAS3-mediated dormancy of ovarian cancer cells, mTOR inhibition by DIRAS3-induced translocation of FOXO3 and TFEB to the nucleus, which stimulated the transcription of multiple autophagy-related genes." (PMID 34832087, 2021). "In ovarian cancer up-regulation of autophagy promotes survival and drug resistance in human xenograft models through expression of DIRAS3." (PMID 33391401, 2021). "In ovarian cancer dormancy model, DIRAS3 expression resulted in the inhibition of signaling through PI3K/AKT and Ras/MAP through enhancing internalization and degradation of the epidermal growth factor receptor." (PMID 33816262, 2021). "In DIRAS3-induced ovarian cancer dormancy model, ARHI re-expression enabled SKOv3 ovarian cancer cells to remain dormant when they were grown in mice as xenografts." (PMID 33816262, 2021). "A preclinical study showed that inhibition with the DIRAS3 peptide does inhibit autophagy in human ovarian cancer cells by binding to BECN1." (PMID 33391401, 2021). "Re-expression of DIRAS3 in a Tet-inducible manner, stimulated autophagy in ovarian cancer xenografts, and led to a reversible inhibition of tumor growth and entry to a dormant state." (PMID 33816262, 2021). "DIRAS3 (or ARHI) is a maternally imprinted tumor suppressor that is frequently downregulated in breast and ovarian cancers." (PMID 33816262, 2021). "We examined the expression of DIRAS3 and autophagy in ovarian cancer cells following nutrient deprivation and the mechanism by which they are upregulated." (PMID 31052266, 2019). "Treatment of dormant DIRAS3 expressing human ovarian cancer cells with chloroquine, a functional inhibitor of autophagy, delays the outgrowth of dormant ovarian cancer cells after downregulating DIRAS3 expression in this xenograft model." (PMID 31052266, 2019). "In more than 80% of positive second looks, persistent ovarian cancer cells express DIRAS3 and are undergoing autophagy." (PMID 31052266, 2019). "Both genetic and pharmacological inhibition of E2F1/4 family members enhance DIRAS3-mediated autophagy in ovarian cancer cells." (PMID 31052266, 2019). "We found that DIRAS3 is downregulated in 60% of ovarian cancers, and was the most downregulated gene compared to normal ovarian epithelial cells." (PMID 31052266, 2019). "DIRAS3 is an imprinted tumor suppressor gene that is downregulated in 62% of ovarian cancers, as well as many other cancers." (PMID 31003488, 2019). "Earlier studies have reported DIRAS3, as a member of the Ras superfamily of small G proteins, to be an anti-oncogene expressed in breast, pancreatic, and ovarian cancers." (PMID 30043279, 2018).
ovarian carcinoma (continued). "An earlier study demonstrated overexpression of DIRAS3 in ovarian cancer cells inhibited both basal and lysophosphatidic acid-induced activation of AKT." (PMID 30043279, 2018). "DNA demethylation agents and/or histone deacetylation inhibitors can recover DIRAS3 activity in breast and ovarian cancers." (PMID 30043279, 2018). "In contrast, Ganoderma tsugae, livin silencing or DIRAS3 overexpression induces autophagic cell death, which increases the chemotherapeutic sensitivity of urothelial cancer, renal carcinoma or ovarian cancer cells, respectively, to CDDP." (PMID 29050305, 2017). "For example, induction of autophagy by ARH-I/DIRAS3 was essential for dormancy of ovarian cancer cell micro metastases in xenograft models." (PMID 28459042, 2017). "Aplasia Ras homolog member I (ARHI; DIRAS3) is an imprinted tumor suppressor gene that is responsible for initiating programmed cell death and inhibiting cancer cell growth, and ARHI is down-regulated in 60% of ovarian cancers." (PMID 27825125, 2016). "Included in the list of 102 genes are genes previously identified as being hypermethylated and down-regulated in cancer (e.g., zinc finger protein 185 in prostate cancer, CAV1 in breast cancer, and DIRAS3 in ovarian cancer)." (PMID 17254359, 2007). "This study explores whether fibronectin (FN) can counteract the growth inhibition induced by DIRAS3 in ovarian cancer cells." (PMID 40862729, 2025). "Treatment of dormant ovarian cancer cells with the autophagy inhibitor chloroquine prevented tumor outgrowth when DIRAS3 levels were reduced, suggesting that autophagy in dormant xenografts appears to be essential for cancer cell survival in a poorly vascularized and nutrient-poor microenvironment." (PMID 40862729, 2025). "Treatment with chloroquine, a functional autophagy inhibitor, significantly reduced the growth of dormant ovarian cancer cells post down-regulation of DIRAS3 expression, emphasizing the crucial role of autophagy in the persistence of dormant cancer cells post-initial surgery and chemotherapy." (PMID 38795254, 2024). "Consequently, DIRAS3-mediated autophagy was enhanced, enabling the maintenance of human ovarian cancer cell growth in a state of growth homeostasis under stress." (PMID 38795254, 2024). "In dormant ovarian cancer cells, DIRAS3 likewise controls the autophagosome initiation complex." (PMID 36805591, 2023). "More than 60% of ovarian cancers exhibit downregulated DIRAS3." (PMID 36805591, 2023). "In addition, Lu and colleagues’ results showed that DIRAS3-induced autophagy contributed to cell survival and tumor dormancy in an ovarian cancer xenograft model, which also supported our findings." (PMID 36805591, 2023). "We observed that ovarian cancer patients bearing a shallow deletion of MIR1305 together with high DIRAS3 expression display a significantly better overall survival compared to that observed in the group of patients with no CNV alterations (possibly expressing high MIR1305)." (PMID 35565270, 2022). "Re-expression of DIRAS3 in ovarian cancer xenografts also induced dormancy and autophagy." (PMID 35754835, 2022). "Previous studies have shown that the overexpression of DIRAS3/ARH-I may drive ovarian cancer cells into a dormant state through the induction of autophagy." (PMID 35565270, 2022). "Also, the restoration of DIRAS3 was previously shown to suppress cell proliferation and stimulate autophagy in ovarian cancer." (PMID 35170376, 2022). "The distinct subgroup of the Ras family member 3 (DIRAS3) gene, also known as ARHI and NOEY2, encodes a small GTPase, which belongs to the Ras superfamily and serves as a tumor suppressor against various cancers including breast and ovarian cancers." (PMID 34063661, 2021). "For instance, mitophagy was activated during DIRAS3-induced dormancy of ovarian cancer cells." (PMID 33816262, 2021).
ovarian carcinoma (continued). "Under nutrient poor conditions DIRAS3 can be transcriptionally upregulated, inducing autophagy that could sustain dormant ovarian cancer cells." (PMID 31052266, 2019). "DIRAS3 is a tumor suppressor gene downregulated in >60% of primary ovarian cancers by genetic, epigenetic, transcriptional and post-transcriptional mechanisms, that upon re-expression can induce autophagy and dormancy in a xenograft model of ovarian cancer." (PMID 31052266, 2019). "To determine whether CEBPα could act as a positive regulator of DIRAS3 transcription during amino acid deprivation in A2780 ovarian cancer cells, we performed chromatin immunoprecipitation experiments following starvation for 2–4 h." (PMID 31052266, 2019). "Although DIRAS3 is an imprinted tumor suppressor gene that is downregulated in ovarian cancer, our previous studies found that matched patient samples where positive second look tumors were removed documented that both DIRAS3 and autophagy were upregulated in the small avascular deposits." (PMID 31052266, 2019). "To determine whether the induction of autophagy following E2F1/4 inhibition was DIRAS3 dependent, we treated A2780 and SKOv3 ovarian cancer cells with DIRAS3 or control siRNA." (PMID 31052266, 2019). "Our group has developed the first inducible xenograft model for tumor dormancy in human ovarian cancer using tet-inducible expression of DIRAS3, demonstrating that autophagy is required to sustain small avascular deposits of human ovarian cancer cells in a nutrient poor environment." (PMID 31052266, 2019). "Re-expression of DIRAS3 in ovarian cancer xenografts also induces dormancy and autophagy." (PMID 31003488, 2019). "We hypothesized that DIRAS3 first binds BECN1 through its switch II region, and that inhibiting this interaction with a DIRAS3-derived peptide capable of binding Beclin1, would decrease autophagy and possibly inhibit dormant ovarian cancer cells." (PMID 31003488, 2019). "Treatment of dormant ovarian cancer cells with chloroquine, a functional inhibitor of autophagy, markedly delays outgrowth of tumors when dormancy is abrogated and growth permitted by downregulation of DIRAS3." (PMID 31052266, 2019). "Previously, we reported that autophagy plays a critical role in the survival of dormant, drug resistant ovarian cancer cells using human xenograft models and correlated the up-regulation of autophagy and DIRAS3 expression in clinical samples obtained during “second look” operations." (PMID 31003488, 2019). "ARHI (DIRAS3), an imprinted tumor suppressor gene, is downregulated in 60% of ovarian cancers." (PMID 26247722, 2015). "Furthermore, DIRAS3 was reported to trigger assembly of autophagosome initiation complex to induce autophagy in dormant, nutrient-deprived ovarian cancer cells." (PMID 25402829, 2014). "In this study we have sought to determine whether nutrient starvation or amino acid deprivation can enhance DIRAS3 expression and induce autophagy in human ovarian cancer cells, providing one mechanism by which DIRAS3 can be upregulated in positive second look tumor specimens." (PMID 31052266, 2019). "Here, we demonstrated that re-expressing DIRAS3 induces autophagy in both SKOv3-DIRAS3 and OVCAR8-DIRAS3 ovarian cancer cells." (PMID 40862729, 2025). "Therefore, DIRAS3-mediated autophagy could promote ovarian cancer cell dormancy." (PMID 36805591, 2023). "Of note, ARH-I (aka DIRAS3) is a tumor suppressor gene maternally imprinted and found to be mono-allelically silenced in more than 60% of ovarian cancers." (PMID 35565270, 2022). "Cancer cell dormancy and autophagy are interconnected at the molecular level through ARH-I (DIRAS3) and BECLIN-1, two tumor suppressors often dysregulated in ovarian cancers." (PMID 35565270, 2022). "Of clinical relevance, we found that ovarian cancer patients bearing a low level of MIR1305 and high expression of DIRAS3 have a longer overall survival compared to patients in which the CNV of MIR1305 was unaltered." (PMID 35565270, 2022).
ovarian carcinoma (continued). "We analysed the expression of frequently downregulated tumour suppressor genes in immune subtype (ie DIRAS3, PEG3, and DLEC1) in the human ovarian cancer cell line SKOV3 and found DIRAS3 was most highly expressed." (PMID 33522069, 2021). "Downregulation of E2F1/4 correlated with the induction of autophagy and upregulation of DIRAS3 protein determined by immunofluorescence staining of LC3 puncta and DIRAS3 protein in A2780, SKOv3, and ES2 ovarian cancer cells." (PMID 31052266, 2019). "Another interesting gene linking autophagy and ovarian cancer is the aplasia ras-homolog member 1 (ARH1; also known as DIRAS3), which codes for a ras-homolog 26 kDa GTPase." (PMID 24877083, 2014). "DIRAS3 is an imprinted tumor suppressor gene with significant homology to RAS that is expressed in normal ovarian and fallopian tube cells but downregulated in approximately 60% of ovarian cancers." (PMID 40862729, 2025). "Treatment of A2780 ovarian cancer cells with DIRAS3 siRNA, but not control siRNA, significantly reduced (p < 0.05) induction of autophagy after amino acid starvation, demonstrated both by reduction of immunofluorescent LC3 puncta and western blot analysis." (PMID 31052266, 2019). "Growth in media lacking amino acids with or without fetal bovine serum (FBS) induces DIRAS3-mediated autophagy in ovarian cancer cells." (PMID 31052266, 2019). "In the current study, we used a model with inducible expression of DIRAS3 in SKOv3 and OVCAR8 ovarian cancer cells to investigate whether FN plays an important role in counteracting the growth inhibition induced by DIRAS3 in ovarian cancer cells." (PMID 40862729, 2025). "Cancer cell dormancy and autophagy are interconnected at molecular level through ARH-I (also known as DIRAS3), a maternally imprinted oncosuppressor that is expressed by normal epithelial cells while it is downregulated in more than 60% of ovarian cancer cases." (PMID 35565270, 2022). "When CEBPα was knocked down with siRNA, we observed that nutrient deprivation was no longer able to upregulate DIRAS3 mRNA expression across several ovarian cancer cell lines and this correlated with a decrease in autophagy induction as determined by immunofluorescence staining of LC3 puncta." (PMID 31052266, 2019).